RPF2 (ribosome production factor 2 homolog)
Description:
Involved in ribosomal large subunit assembly. May regulate the localization of the 5S RNP/5S ribonucleoprotein particle to the nucleolus.
Synonyms: BXDC1; FLJ21087; bA397G5.4
Tractability: Small molecule: a structure with a bound ligand is known. PROTAC: ubiquitination databases record sites on it; its protein half-life has been measured.
Gene: Protein-coding gene on chromosome 6 (110,982,015 to 111,028,263, forward strand). Ensembl gene ENSG00000197498.
Subcellular location: Nucleus, nucleolus
Subcellular location (Human Protein Atlas): Nucleoli; Nucleoli rim; Mitotic chromosome; Nucleoplasm
Gene Ontology:
Molecular function: 5S rRNA binding; protein binding; RNA binding; rRNA binding
Biological process: protein localization to nucleolus; ribosomal large subunit biogenesis; maturation of LSU-rRNA from tricistronic rRNA transcript (SSU-rRNA, 5.8S rRNA, LSU-rRNA); maturation of LSU-rRNA; ribosomal large subunit assembly; rRNA processing
Cellular component: chromosome; nucleolus
Genetic constraint (gnomAD): Loss-of-function variants: 9 observed, 19.32 expected, observed/expected ratio (o/e) 0.47, 90% interval 0.28 to 0.81. The upper end of that interval is the gene's LOEUF score, 0.81, which puts it in group 3 of 6, group 1 being the genes least tolerant of losing a copy. Missense variants: 195 observed, 216.82 expected, observed/expected ratio (o/e) 0.9, 90% interval 0.8 to 1.01. Synonymous variants: 82 observed, 79.51 expected, observed/expected ratio (o/e) 1.03, 90% interval 0.86 to 1.24.
Homologues: Orthologues: chimpanzee RPF2 (100% identical), macaque RPF2 (99% identical), pig RPF2 (96% identical), guinea pig RPF2 (96% identical), rabbit RPF2 (96% identical), dog RPF2 (94% identical), mouse Rpf2 (92% identical), rat Rpf2 (88% identical), tropical clawed frog rpf2 (79% identical), zebrafish rpf2 (71% identical), Drosophila melanogaster Non3 (47% identical), Caenorhabditis elegans Y54E10A.10 (40% identical).
Diseases named in the same sentence as RPF2 in open-access papers:
RPF2 is named in the same sentence as 7 diseases in open-access papers, as found by Europe PMC text mining. Sharing a sentence is not in itself a finding about the gene and the disease. The quoted sentences say what the papers report.
colorectal cancer (4 papers, 2022 to 2025). A primary or metastatic malignant neoplasm that affects the colon or rectum. "RPF2 can promote chemotherapy resistance in colorectal cancer cells." (PMID 40625890, 2024). "Again of interest, silencing the protein, suggest that RPF2 may play a role in the epithelial-to-mesenchymal (EMT) transition in colorectal cancer cells." (PMID 36171564, 2022). "In colorectal cancer, RPF2 is significantly overexpressed, promoting epithelial-mesenchymal transition (EMT) via the AKT/GSK-3β signaling pathway, thereby enhancing migration and invasion of colorectal cancer cells in vitro and vivo." (PMID 40577282, 2025).
liver cancer (1 paper, 2025). An epithelial or non-epithelial malignant neoplasm that arises from the liver. "RPF2 overexpression facilitates cell proliferation, migration, and invasion, contributing to the progression of liver cancer." (PMID 40577282, 2025). "Moreover, a recent study has indicated that RPF2 was highly expressed in liver cancer tissues compared to adjacent normal tissues." (PMID 40577282, 2025). "While this may seem counterintuitive, especially considering RPF2’s role in promoting liver cancer progression, this correlation does not imply a direct causal relationship." (PMID 40577282, 2025).
infection (3 papers, 2015 to 2022). The state of being infected such as from the introduction of a foreign agent such as serum, vaccine, antigenic substance or organism. "In contrast, almost 100 transcripts related to genes typically involved in viral protein translation during infection (e.g. rps2, 12, 14; wdr12; rpf2; nip7; eif4; eif4ebp3l; eif4a3; eif4ea; eif4b) were down-regulated." (PMID 35710351, 2022).
cancer (2 papers, 2025). A tumor composed of atypical neoplastic, often pleomorphic cells that invade other tissues. "In cultured cells, RPF2 promoted cancer cell proliferation, migration, and invasion." (PMID 40917497, 2025).
tumor (2 papers, 2025). "Co-immunoprecipitation (CO-IP) analysis further confirmed the physical interaction between RPF2 and UBTF at the cell line and tumor tissue levels." (PMID 40917497, 2025). "Thus, we tested whether high RPF2 expression increased tumor proliferation and migration ability." (PMID 40917497, 2025). "It rather suggests that RPF2 may promote tumor progression through alternative pathways independent of VEGFR, highlighting the potential for targeting different pathways in HCC treatment." (PMID 40577282, 2025). "In this study, we suggested that RPF2 overexpression could enhance the catalytic activity of RNA pol I via strengthening the expression and binding activity of UBTF, thereby up-regulating rRNAs production and ribosome formation, ultimately promoting tumor proliferation and invasion." (PMID 40917497, 2025).
RPF2 also shares sentences with these, for which no sentence is quoted: depression (1 paper); kidney (1).